CCND1 (cyclin D1)
Diseases named in the same sentence as CCND1 in open-access papers (continued):
Sharing a sentence is not in itself a finding about the gene and the disease.
metastatic colorectal cancer (2 papers, 2010 to 2024). "The significance of BRAF mutations, microsatelite instability (MSI) status and cyclin D1 expression in patients with metastatic colorectal cancer (mCRC) was evaluated." (PMID 20485284, 2010).
microphthalmia (2 papers, 2009 to 2016). Congenital or developmental anomaly in which the eyeballs are abnormally small. "Unlike the microphthalmia seen in the cyclin D1–null mouse, no gross retinal phenotype has been identified in the cyclin D2–null mouse." (PMID 27957530, 2016).
Myocardial fibrosis (2 papers, 2022 to 2024). "Phosphorylated STAT3 into the nucleus can accelerate the transcription and expression of the CCND1 gene, which drives the cell cycle of cardiac fibroblasts from the G1 phase to the S phase and accelerates myocardial fibrosis." (PMID 38402401, 2024).
non-alcoholic fatty liver disease (2 papers, 2020 to 2022). "CCND1 is a key cell-cycle regulatory protein, and overexpression of CCND1 was observed in aged non-alcoholic fatty liver disease mice." (PMID 35267929, 2022).
non-melanoma skin carcinoma (2 papers, 2018 to 2024).
oral mucositis (2 papers, 2017 to 2024). Inflammation of the mucous membranes of any of the structures in the mouth. "- CCND1 rs9344 was related to grade 3–4 acute radiation-induced oral mucositis in recessive model among patients <51 years old." (PMID 38473311, 2024). "CCND1 rs9344 was related with grade 3–4 acute radiation-induced oral mucositis in recessive model among patients < 51 years old, and it was also related with grade 3–4 acute radiation-induced myelosuppression in additive and recessive models among patients with BMI < 22.8." (PMID 28445979, 2017). "In some subgroups, cyclin D1 gene CCND1 rs9344 and inhibitor of κB kinase gene IKBKB rs12676482 were related with the grade 3–4 acute radiation-induced myelosuppression, and CCND1 rs9344 was also associated with grade 3–4 acute radiation-induced oral mucositis." (PMID 28445979, 2017).
osteoarthritis (2 papers, 2024). A noninflammatory degenerative joint disease occurring chiefly in older persons, characterized by degeneration of the articular cartilage, hypertrophy of bone at the margins and changes in the synovial membrane. "It was reported that CCND1 and SNHG16 were upregulated in the cartilage tissues of osteoarthritis, and SNHG16 could promote the progress of osteoarthritis by regulating miR‐93‐5p/CCND1 axis." (PMID 39555740, 2024).
ovarian endometrioid carcinoma (2 papers, 2012 to 2025). "In the present study, we established the human ovarian endometrioid carcinoma cell line JFE-21 by constitutive expression of exogenous CDK4R24C, cyclin D1 and TERT genes." (PMID 39878900, 2025). "Thus, constitutive expression of CDK4R24C, cyclin D1 and TERT genes may be an option for establishing cell lines from low-grade cancers, including ovarian endometrioid carcinoma." (PMID 39878900, 2025).
pituitary (2 papers, 2018 to 2019). "The results revealed that protein levels of β-catenin, c-myc, and cyclin D1 were negatively regulated by CLRN1-AS1, indicating that CLRN1-AS1 potentially inactivated the Wnt/β-catenin signaling pathway in pituitary prolactinoma." (PMID 31235696, 2019).
primary hyperparathyroidism (2 papers, 2011 to 2026). Hyperfunction of the parathyroid glands resulting in the overproduction of parathyroid hormone. "Known risk factors for primary hyperparathyroidism include abnormalities of the PRAD1, MEN1, and HRPT2 genes that encode for cyclin D1, menin, and parafibromin, respectively." (PMID 21776381, 2011).
prostate intraepithelial neoplasia (2 papers, 2014 to 2025). A neoplastic proliferation of the epithelial cells that line the acini and the ducts of the prostate gland. "Additionally, β-catenin stabilization and nuclear localization result in the upregulation of the β-catenin target genes cyclin D1 and c-myc, which can lead to the formation of the prostatic intraepithelial neoplasia (PIN)-like phenotype." (PMID 25360740, 2014).
retinal degeneration (2 papers, 2015 to 2023). Degeneration of the retina. "We showed that fullerol increased the number of MG cells that entered the cell cycle (Ccnd1-labeled MG) during light-induced retinal degeneration." (PMID 37816275, 2023).
Sarcoids (2 papers, 2022 to 2023). "The GCs of sarcoidosis, sarcoid-like lesion, and tuberculosis were consistently cyclin D1-negative." (PMID 37509363, 2023).
serous ovarian cancer (2 papers, 2013 to 2022). "GEO-based analysis of microarray GSE189717 showed ectopic expression of MYC, EGFR, and CCND1 in platinum-resistant high-grade serous ovarian cancer cell lines." (PMID 35739532, 2022). "Significantly high levels of MYC, EGFR, and CCND1 were detected in platinum-resistant high-grade serous ovarian cancer cell lines." (PMID 35739532, 2022). "To further validate the relevance of MYC, EGFR, and CCND1 to platinum chemotherapy response, we analyzed their differential expression between platinum-sensitive and platinum-resistant high-grade serous ovarian cancer cells based on GEO microarray (GSE189717)." (PMID 35739532, 2022).
signet ring cell adenocarcinoma (2 papers, 2013 to 2024). "Compared to non-signet ring cell adenocarcinoma, a higher frequency of mutations in CCND1 (P = 0.024) was observed in signet ring cell adenocarcinoma." (PMID 38704377, 2024).
Splenomegaly (2 papers, 2021). Abnormal increased size of the spleen. "This patient presented with splenomegaly, subcutaneous and muscular lesions, and retroperitoneal/pelvic lymphadenopathies, with BM (40%) involvement and strong CCND1 staining in the BM biopsy." (PMID 34001881, 2021).
squamous cell carcinoma of the vulva (2 papers, 2022 to 2023).
status epilepticus (2 papers, 2015 to 2025). Status epilepticus is defined as a continuous seizure lasting more than 30 min, or two or more seizures without full recovery of consciousness between any of them. "Recently, we have reported that LIM kinase 2 (LIMK2) involves programmed necrotic neuronal deaths induced by aberrant cyclin D1 expression following status epilepticus (SE)." (PMID 26438559, 2015).
teratoma (2 papers, 2013 to 2018). A non-seminomatous germ cell tumor characterized by the presence of various tissues which correspond to the different germinal layers (endoderm, mesoderm, and ectoderm). "Taken together, the results suggested that the downregulation of Ccnd1 caused by Dnd1-mediated expression of Ezh2 may be crucial for the suppression of teratoma development in germ cells." (PMID 29378702, 2018). "A previous study reported that Ccnd1 expression was undetectable in embryonic germ cells, but was aberrantly expressed in E15.5 testicular germ cells in the teratoma-susceptible M19 mouse strain, and Ccnd1 knock-out M19 mice showed a decreased incidence of teratoma." (PMID 29378702, 2018). "Interestingly, the percentage of germ cells, which continue to express Ccnd1 correlates with the risk of the respective mouse strain to develop teratoma." (PMID 23967156, 2013). "Our results from the present study suggest that Ccnd1 is controlled by Dnd1 via epigenetic regulation, and it is involved in teratoma formation." (PMID 29378702, 2018). "Our results showed a molecular linkage between Dnd1, its target, enhancer of zeste homolog 2 (Ezh2), as well as a target of Ezh2, cyclin D1 (Ccnd1), in the conversion of embryonic germ cells into teratoma-forming cells." (PMID 29378702, 2018). "Previous studies have detected teratoma-forming cell clusters in Dnd1ter/ter testes as early as E16.5 by analyzing E-cadherin expression and Ccnd1 expression in E15.5 testicular germ cells in M15 mice." (PMID 29378702, 2018). "In our analysis, clusters of teratoma-forming cells in which Ccnd1 expression was upregulated were obvious in Dnd1ter/ter testes at E17.5." (PMID 29378702, 2018).
Thrombocytopenia (2 papers, 2022 to 2023). A reduction in the number of circulating thrombocytes.
thymoma (2 papers, 2015 to 2024). A neoplasm arising from the epithelial cells of the thymus. "Indeed, Axin2, Cyclin D1 and c-Myc were upregulated in the manifest thymomas compared to the CD45− thymic stromal cells isolated from non-Tg thymi." (PMID 26101855, 2015).
uterine cancer (2 papers, 2006 to 2020). Primary or metastatic malignant neoplasm involving the uterine corpus and/or the cervix. "Nuclear expression of cyclin D1 is rarely observed in healthy endometrial tissue, while the majority of uterine cancers express cyclin D1, and cyclin D1 expression predicts poor survival." (PMID 33378353, 2020). "Firstly, we performed similar experiments in the SK-UT-1B uterine cancer cell line that has been shown previously to be defective in cyclin D1 degradation." (PMID 16503970, 2006).
uveal melanoma (2 papers, 2011 to 2021). A melanoma derived from melanocytes of the uveal tract. "It has been shown in the past that a target of this pathway, CCND1, responsible for encoding cyclin D1, is overexpressed in uveal melanomas leading to phosphorylation and inactivation of the retinoblastoma tumour suppressor gene in uveal melanomas." (PMID 21773036, 2011).
viral myocarditis (2 papers, 2021 to 2022). Myocarditis that is caused by an infection with a viral agent. "We found three genes (CASP8, ACTG1, and CCND1) that were significantly associated with viral myocarditis." (PMID 34722003, 2021).
von Hippel-Lindau disease (2 papers, 2014 to 2024). An autosomal dominant disorder caused by pathogenic variants in the VHL gene, leading to an increased risk of various benign and malignant tumors, including hemangioblastomas, retinal hemangiomas, endolymphatic sac tumors, renal cell carcinoma, and pheochromocytomas. "Whole Exome Sequencing Analysis Reveals: A point mutation in the DLST Gene (c.330 + 14A>G), potentially linked to PGL Type 7, and a mutation in the Cyclin D1 (CCND1) Gene (c.575–13C>T), potentially associated with Von Hippel-Lindau Syndrome." (PMID 38835385, 2024).
abortion (1 paper, 2022). the ending of pregnancy by removing a fetus or embryo before it can survive outside the uterus. "Relevant clinical experiments have also confirmed that the expression of Cyclin D1 in chorionic villus cells and decidual cells of spontaneous abortion patients is lower than that of normal pregnancy patients, and the number of trophoblast cells decreased and cell apoptosis increased." (PMID 36086762, 2022).
acute kidney injury (1 paper, 2022). Sudden and sustained deterioration of the kidney function characterized by decreased glomerular filtration rate, increased serum creatinine or oliguria. "Unlike the reparative role of cell cycle progression following acute kidney injury, these data suggest that blocking cell cycle progression by inhibiting CDK4/6, but not cyclin D1, protects against chronic kidney injury." (PMID 35730565, 2022).
acute liver failure (1 paper, 2023). Rapid deterioration of liver function causing encephalopathy and coagulopathy. "In the second model in which C57/B6 mice were injected with a single dose of acetaminophen (APAP) to induce acute liver failure, similar observations were made that Trib1 expression was down-regulated at 1d and 2d in the liver after APAP injection, which mirrored PCNA/cyclin D1/CDK4 up-regulation." (PMID 37355685, 2023).
acute myelomonocytic leukemia (1 paper, 2025). "SFX-01 also induced STAT1 phosphorylation as well as loss of cyclin D1 expression in the human acute myelomonocytic leukemia GDM-1 cell line that expresses an activating Shp2 mutation associated with JMML and NS." (PMID 40640547, 2025).
acute pancreatitis (1 paper, 2021). An acute inflammatory process that leads to necrosis of the pancreatic parenchyma. "Reg3a has been shown to regulate keratinocyte proliferation and differentiation after skin injury via Reg-Extl3-PI3K-Cyclin D1 pathway, while Reg3g downregulates the Stat3-Socs signaling which may result in enhanced apoptosis in acute pancreatitis." (PMID 34926699, 2021).
adenomyosis (1 paper, 2022). The growth of endometrial tissue inside the muscular wall of the uterine corpus. "In the present validation, CCND1 mRNA was significantly increased in both the eutopic endometrium (P = 0.044) and myometrium (P = 0.002) of women with adenomyosis, consistent with a role for CCND1 in endometrial cell proliferation in women with adenomyosis." (PMID 35773139, 2022). "CCND1 is a key component of PRL signalling and may be a factor in endometrial cell proliferation and adenomyosis." (PMID 35773139, 2022).
adenosarcoma (1 paper, 2023). A low grade malignant neoplasm characterized by the presence of a benign epithelial component (tubular and cleft-like glands) and a low grade sarcomatous component that contains varying amounts of fibrous and smooth muscle tissues. "Five (45.5%) of the 11 high-grade adenosarcomas and 3 (33.3%) of the 9 low-grade adenosarcomas showed cyclin D1 positivity." (PMID 35876683, 2023). "Sharma and Prachi reported that one adenosarcoma with SOG showed cyclin D1 positivity." (PMID 35876683, 2023).
adrenocortical tumor (1 paper, 2022). "By contrast, in adrenocortical tumor cells, vasopressin blocks the cell cycle and reduces cell growth by inhibiting cyclin D1." (PMID 35874817, 2022).
allergic asthma (1 paper, 2024). A asthma with a basis in a pathological type I hypersensitivity reaction. "The present MR results suggested the presence of associations between the risk of allergic asthma and BAX, CASP3, CCND1, ICAM1, PEBP1, RAF1, and ERBB2 expression." (PMID 39769348, 2024). "The current results suggested that CASP3, CCND1, ICAM1, RAF1, and ERBB2 expression are causally related to the risk of allergic asthma." (PMID 39769348, 2024). "Based on the inverse variance weighted method, the MR analysis provided evidence of associations between allergic asthma and BAX, CASP3, CCND1, ERBB2, ICAM1, PEBP1, and RAF1 in the blood." (PMID 39769348, 2024).
anal tumor (1 paper, 2017). "The others pretreatment variables with significant predictive value are anal tumor distance, cyclin D1, p21, EGFR and VEGF in biopsies and neutrophil lymphocyte ratio in blood samples." (PMID 28938543, 2017).
anaplastic gliomas (1 paper, 2018). "As expected from its role in cell proliferation, Cyclin-D1 expression increases in anaplastic gliomas and especially in OGs showing a correlation with proliferative index." (PMID 29489901, 2018).
anaplastic large cell lymphoma (1 paper, 2008). Anaplastic large cell lymphoma (ALCL) is a rare and aggressive peripheral T-cell non-Hodgkin lymphoma, belonging to the group of CD30-positive lymphoproliferative disorders, which affects lymph nodes and extranodal sites. "This is consistent with previous study that targeting Stat3 signaling with dnStat3 suppresses cell-cycle-related genes, including cyclin-D1, in ALK-positive anaplastic large cell lymphoma." (PMID 18939995, 2008).
androgenic alopecia (1 paper, 2023). "The level of ALDH1, β-catenin, cyclin D1, and PKM2 decreased by 73.6%, 37.4%, 69.3%, and 16.4%, respectively, in the androgenic alopecia control compared to the normal control." (PMID 36839662, 2023).
angiomyolipoma (1 paper, 2009). A neoplasm with perivascular epithelioid cell differentiation often associated with tuberous sclerosis. "Cyclin D1 protein expression is 4-fold higher in angiomyolipomas kidney tissue of patients with TSC compared to control samples suggesting that partial loss of tuberin is sufficient to upregulate cyclin D1." (PMID 19265534, 2009).
Anxiety (1 paper, 2024). Intense feelings of nervousness, tension, or panic often arise in response to interpersonal stresses. "The conduction of the experiment with female rats could be a subject of future research, as memory, anxiety levels, as well as the BDNF and Cyclin D1 expression, can be influenced by the natural fluctuations in the sex hormone levels during the ovarian cycle in female rats." (PMID 39727966, 2024).
aortic aneurysm (1 paper, 2023). A ruptured aneurysm located in the wall of the proximal portion of the descending aorta proceeding from the arch of the aorta. "Phenotypic changes in VSMCs in aortic aneurysms can lead to an increased expression of various genes and proteins involved in these processes, such as matrix metalloproteinases (MMPs), transforming growth factor-β (TGF-β) and cyclin D1." (PMID 37958985, 2023).
aortic valve calcification (1 paper, 2024).
Arrhythmia (1 paper, 2025). Any cardiac rhythm other than the normal sinus rhythm. "Furthermore, downstream genes (MYH6, MYH7, TNNT2, NKX2-5, and CCND1) regulated by SFRP4 partake in ICM-related diseases like HF and arrhythmias." (PMID 40066352, 2025).
atypical teratoid rhabdoid tumor (1 paper, 2021). Atypical teratoid rhabdoid tumor (ATRT) is a highly malignant central nervous system (CNS) rhabdoid tumor (RT) found almost exclusively in children. "miR-17-92 (miR-19a, miR-17 and miR-20a): Increased MIR17HG expression, a gene encoding a cluster of six miRNAs (miR-17-92) conferred sensitivity to palbociclib treatment in atypical teratoid rhabdoid tumors (ATRTs) via suppression of the cyclin D1 protein." (PMID 34439268, 2021).
Azoospermia (1 paper, 2020). Absence of any measurable level of sperm,whereby spermatozoa cannot be observed even after centrifugation of the semen pellet. "Some target genes of the downregulated miRNAs, such as ACVR2A, CCND1, CCNE2, HMGA2, BMI1, NR2C2 and BCL2, have been associated with gonadal development, and germ cell maintenance through different pathways which could be relevant to the molecular mechanisms affected in KS patients with azoospermia." (PMID 32651451, 2020).
basosquamous carcinoma (1 paper, 2024). A basal cell carcinoma which displays squamous differentiation. "In basal cell and basosquamous carcinomas, cyclin D1 positivity was identified as a marker of aggressive behavior." (PMID 38742684, 2024).
Becker muscular dystrophy (1 paper, 2012). Becker muscular dystrophy (BMD) is a neuromuscular disease characterized by progressive muscle wasting and weakness due to degeneration of skeletal, smooth and cardiac muscle. "In addition, we also evaluated the mRNA expression of Sp1 and Cyclin D1 expression in mdx mice and patients with mild Becker muscular dystrophy (BMD) and severe Duchenne muscle dystrophy (DMD)." (PMID 22911796, 2012).
benign breast disease (1 paper, 2009). "PPARγ expression is reduced in human benign breast disease and cancers correlating with increased cyclin D1 abundance." (PMID 19356226, 2009).
benign meningioma (1 paper, 2023). A grade I, slowly growing meningioma. "Cyclin D1 protein expression (immunoreactivity) was higher in atypical than in benign meningiomas, accordingly to observations of lower hsa-miR-193b-3p levels in GII tumors." (PMID 37686289, 2023).